MGMT (O-6-methylguanine-DNA methyltransferase)
Diseases named in the same sentence as MGMT in open-access papers (continued):
Sharing a sentence is not in itself a finding about the gene and the disease.
glioma (continued). "We tested the combination of TMZ and BAY-1895344 or AZ-20 in an isogenic glioma cell line model using U251 wild-type cells and U251 shMSH2 cells, which are both MGMT-." (PMID 35388070, 2022). "On the other hand, Oldrini and colleagues (2021) reported that MGMT genomic rearrangements carried by a subset of recurrent gliomas led to MGMT overexpression and TMZ resistance in vitro and in vivo, independently from changes in its promoter methylation." (PMID 36499000, 2022). "For example, the anti-tumor effect of TMZ with ATMi or PARPi is enhanced in IDH1 mutant gliomas, and TMZ increases ATRi sensitivity in MGMT-deficient GB cells." (PMID 35406593, 2022). "MGMT methylated glioma is more sensitive to alkylated drugs, enabling MGMT to be an emerging target for increasing the sensitivity of chemotherapy in glioma." (PMID 35855654, 2022). "Although MGMT methylation was not tested by molecular detection in this study, the level of MGMT expression can still reflect the sensitivity of glioma to temozolomide chemotherapy." (PMID 36483042, 2022). "Fourth, some important glioma-related biomarkers like O6-methylguanine-DNA methyltransferase (MGMT) methylation and telomerase reverse transcriptase (TERT) mutation status were not included in the study due to incomplete pathological information." (PMID 36052263, 2022). "In summary, we illustrated that exosomal circWDR62 contributed to the TMZ resistance and malignant progression of glioma by sponging miR-370-3p via modulation of MGMT expression." (PMID 35817771, 2022). "Our experiments show that TMZ leads to the unfavorable enrichment of tumor cells with increased proliferation or migration, further challenging the practice of the TMZ therapy of gliomas with the unmethylated MGMT promoter." (PMID 35563629, 2022). "On the other hand, numerous studies have reported that gliomas have specific molecular parameters, such as IDH-mutation and MGMT promoter methylation." (PMID 35478847, 2022). "For instance, the promoter hypermethylation and epigenetic silencing of the O6-methylguanine-DNA methyltransferase (MGMT) gene have become a classical biomarker for temozolomide resistance glioma." (PMID 36727078, 2022). "Another study performed in low-grade gliomas reported a consistent signature in the methylation of MGMT, MLH3, RAD21, and SMC4 promoter region predictive value for response to temozolomide." (PMID 35359376, 2022). "Further, we evaluated the association of quantitative contrast enhancement with prognostic molecular markers such as isocitrate dehydrogenase (IDH) and O6-methylguanine-DNA-methyltransferase (MGMT) status in gliomas." (PMID 36292183, 2022). "CGGA: 686 glioma samples; TCGA: 592 glioma samples; clinical features: grade, gender, age, IDH mutation, 1p19q codeletion, MGMT, radiotherapy, and chemistry." (PMID 35711921, 2022). "On univariate Cox analysis, the WHO grade, age, IDH mutation status, 1p/19q deletion status, MGMT promoter methylation status, and CLCF1 expression were closely related to the prognosis of glioma in TCGA and CGGA datasets." (PMID 35265072, 2022). "In this study, we demonstrate that GMFG can be a complementary marker when combined with the methylated status of MGMT promoter for predicting TMZ response in gliomas." (PMID 35845613, 2022). "We also set to test the extracted GA-RF feature set to classify the MGMT methylation status for the low-grade glioma (LGG) dataset." (PMID 35927323, 2022). "The previous work of this study showed that RIP2 was involved in the resistance of gliomas to TMZ by inducing the expression of DNA repair enzyme MGMT." (PMID 36184801, 2022). "MGMT is a critical DNA repair gene, and evidence indicates that MGMT expression correlates with chemoresistance and poor prognosis in multiple cancers, including glioma." (PMID 35817771, 2022).
glioma (continued). "The identified interconnection of the processes of glycolysis with methylation of MGMT promoter makes it possible to use special features of glioma carbohydrate metabolism to improve the efficiency of chemotherapy." (PMID 35625744, 2022). "In CheckMate-498, a randomized clinical trial, nivolumab combined with bevacizumab and nivolumab combined with chemoradiotherapy in newly diagnosed glioma patients with O6-methylguanine DNA methyltransferase (MGMT) promoter unmethylation were both ineffective." (PMID 36778912, 2022). "In our studies, high PLK1 level was also associated with clinical features such as grade, IDH mutation status, 1p/19q co-deleted status, and methylation status of MGMT promoter in glioma." (PMID 36618405, 2022). "Twelve out of thirty-seven glioma samples were identified as having MGMT promoter methylation (32%)." (PMID 36050369, 2022). "IDH mutation is a principal marker of low-grade glioma (LGG), while MGMT promoter methylation is a predictor of temozolomide drug response." (PMID 35938030, 2022). "The MGMT gene is involved with DNA repair and in the resistance to alkylating drugs of glioma cells." (PMID 36009577, 2022). "In glioma cells, the level of MGMT protein expression has been related to the efficacy of alkylating agents." (PMID 36009577, 2022). "A significant correlation was also found between MGMT gene methylation and the glutathione transferase levels in glial tumor tissue (Rho = 0.620)." (PMID 36289655, 2022). "The literature demonstrates the capability of 18F-FDOPA-PET to differentiate low- from high-grade gliomas as well as the presence of an IDH-mutation, the 1p/19q co-deletion status and the MGMT methylation status." (PMID 36434486, 2022). "MGMT promoter methylation predicts less aggressive glioma behavior for both IDH-mutated and IDH-wild-type gliomas." (PMID 35982952, 2022). "Considering that, the present study aimed to explore the prognostic significance of the MGMT promoter methylation status within the >50 years cohort of high-grade glioma patients." (PMID 36361838, 2022). "The other lncRNAs from the m5C LPS all showed significant differences in subgroups of WHO grade, IDH, 1p19q codeletion and MGMT methylation, indicating their differential roles in gliomas." (PMID 35372082, 2022). "MGMT-methylated gliomas exhibited significantly higher nADC values than MGMT-unmethylated gliomas (P = 0.021)." (PMID 36471242, 2022). "We first determined the expression HOXC6, MMP9, SHOX2 and MYOD1 in glioma tissues with promoter-methylation and promoter-unmethylation of MGMT." (PMID 36118887, 2022). "Our results demonstrate for the first time that exosome-mediated delivery of circWDR62 can promote TMZ resistance and malignant progression via targeting of the miR-370-3p/MGMT axis in vitro and in vivo in glioma, providing a new therapeutic strategy." (PMID 35817771, 2022). "In recent years, with the rapid development of molecular pathology, it has been found that several molecular markers (IDH, 1p19q codeletion and MGMT) have an impact on the OS of patients with glioma." (PMID 35227235, 2022). "Since lower grade, 1p/19q codeletion, MGMT promoter methylation, and IDH1 mutation were the major favorable prognostic markers for glioma, a subgroup analysis based on the status of these parameters was performed in both TCGA and CGGA cohort." (PMID 35990696, 2022). "Lastly, RAD18 or O6-methylguanine-DNA methyltransferase (MGMT) overexpression abolished the sensitization effect of HDAC inhibition on TMZ-exposed glioma cells." (PMID 35365623, 2022). "Previously, we found that RIP2 regulates MGMT expression through the NF‐κB signaling pathway, thereby mediating the resistance of glioma cells to TMZ." (PMID 36184801, 2022). "MGMT promoter methylation status and 1p19q co-deletion are molecular features of good prognosis in glioma, and patients with methylation on MGMT promoters usually have a better response to chemotherapy." (PMID 35646664, 2022).
glioma (continued). "The two molecular biomarkers of significant interest that have translated into clinical practice are IDH and MGMT, which are responsible for the epigenetic alterations in grade 4 gliomas." (PMID 36675733, 2022). "Unmethylated MGMT promoter creates a resistant glioma phenotype by restoring the DNA alkylation and serves as an essential contributor to chemotherapy failure." (PMID 35720326, 2022). "MGMT promoter methylation is essential to evaluate glioma patients’ sensitization to alkylating agents for personalized and precise treatment and evaluate prognosis." (PMID 36092717, 2022). "And we also found that overactive ROCK2 enhanced homologous recombination repair (HR) in TMZ-resistant (TMZ-R) glioma cell lines with low MGMT expression." (PMID 35145081, 2022). "MGMT promoter hypermethylation leads to downregulation of MGMT expression; it is present in about 40% of glioma grade 4 cases, and about 17% of GBM show complete absence of MGMT activity." (PMID 35565362, 2022). "Accordingly, it was found that the parental glioma cells that were sensitive to temozolomide (TMZ) had lower MGMT mRNA levels which corresponded with higher sensitivity to TMZ." (PMID 35682901, 2022). "MGMT methylated gliomas showed a lower density in comparison to MGMT unmethylated gliomas which was however not significant (p = 0.11–0.22)." (PMID 36292183, 2022). "Next, we performed an integrated analysis of EGFR amplification and molecular glioma hallmarks: IDH1/2 mutations, TERT promoter mutations, MGMT promoter methylation, and LOH 1p/19q." (PMID 35453544, 2022). "Considering MGMT promoter methylation, indistinctly enhancing tumor margins have been observed more frequently in methylated than unmethylated gliomas (45.5% versus 7.7%, respectively)." (PMID 36289752, 2022). "The drug resistance protein MGMT plays an important role in glioma cells; therefore, we examined the expression changes of MGMT and its upstream signal protein β-catenin." (PMID 35545654, 2022). "Currently, IDH and MGMT methylation are the only two molecular features more widely implemented in treating glioma patients." (PMID 36551786, 2022). "IDH mutations and methylation of the O6-methylguanine-DNA methyltransferase (MGMT) promoter, both important prognostic factors in glioma, occurred in more than 70% of LGG and 50% of grade IV astrocytoma, respectively." (PMID 36292767, 2022). "A prognostic effect of MGMT promoter methylation in patients with lower-grade or higher-grade glioma has already been observed." (PMID 36873808, 2022). "We found the high‐risk score is strongly associated with well‐known malignant features of gliomas, such as the mesenchymal subtype, IDH‐wildtype, 1p/19q non‐codeletion and MGMT promoter unmethylated status." (PMID 35615996, 2022). "In our study, bioinformatics analysis, rescue assays and in vivo experiments all confirmed that MGMT is a direct target gene of the circWDR62/miR-370-3p axis in glioma." (PMID 35817771, 2022). "MGMT is a DNA repair protein that is overexpressed in glioma cells and can repair the TMZ-induced DNA damage, resulting in TMZ resistance in glioma cells." (PMID 36059989, 2022). "One of the major mechanisms of TMZ resistance induced by these glioma stem cells is due to the enhanced activity of a DNA repair enzyme known as O6-methylguanine-DNA-methyltransferase (MGMT) in the cells." (PMID 36329899, 2022). "In our study, there was no statistical correlation of serum miR-4297 levels with methylated MGMT status for all the patients; whereas miR-4297 levels positively correlated with MGMT protein expression on glioma specimen in the female subgroup." (PMID 35968285, 2022). "Studies on the relationship between MGMT promoter methylation and MRI imaging of glioma are insufficient, and predicting the methylation status of the MGMT promoter in glioma with MR images is still a challenging task, requiring further research." (PMID 35743511, 2022).
glioma (continued). "The protein level of MGMT was found to be inversely related to the chemosensitivity of gliomas to alkylating agents." (PMID 35053068, 2022). "Clinical studies have shown that MGMT promoter hypermethylation in approximately half of gliomas appears to predict a better treatment response to TMZ." (PMID 35847909, 2022). "In the TCGA dataset, we found that GMFG expression was significantly higher in gliomas with unmethylated MGMT promoter than in those with methylated MGMT promoter." (PMID 35845613, 2022). "Mutant IDH1 was shown to promote the glioma cytosine–phosphate–guanine (CpG) island methylator phenotype (G-CIMP) in gliomas, which are often characterized by the epigenetic silencing of MGMT." (PMID 36361838, 2022). "PsP has been found more frequently in gliomas with hypermethylation of the O-6-methylguanine-DNA methyltransferase (MGMT) gene promoter, which is present in up to ~45% of GBM." (PMID 37492665, 2022). "In glioma, methylation of the O-6-methylguanine-DNA methyltransferase (MGMT) promoter indicates an improved patient treatment response and, therefore, better prognosis." (PMID 36050369, 2022). "Growing numbers of studies uncovered that the methylation status of MGMT gene promoter is the key factor that determines the MGMT expression, and can influence the efficacy of chemotherapy as well as the prognosis of glioma patients." (PMID 35276059, 2022). "A few molecular markers have been applied in clinical practice for glioma, such as IDH mutations, codeletion of 1p/19q, and MGMT promoter methylation, which are considered to represent a better prognosis." (PMID 36353126, 2022). "Standard glioma biomarker data collected into BRAIN includes 1p19q codeletion, IDH mutation, MGMT methylation, ATRX mutation and TERT promotor mutation with a free text field to capture other biomarkers of interest." (PMID 35655179, 2022). "Isocitrate dehydrogenase (IDH) mutation, 1p/19q codeletion status, and O6-methylguanine DNA methyltransferase (MGMT) promoter methylation have all been well demonstrated to relate with the malignancy of gliomas." (PMID 35265072, 2022). "As compared to males, our present study presented the prominent increase of serum miR-4297 in parallel with MGMT protein on tumor tissues in females, which is probably attributed to sex disparities in MGMT expression in glioma." (PMID 35968285, 2022). "DWI metrics can predict glioma grading and IDH mutation noninvasively, but have limited use in detecting TERT mutation and MGMT methylation." (PMID 36471242, 2022). "The methylation status of the MGMT promoter has emerged as a key predictive biomarker of glioma and a potential predictor of response to temozolomide." (PMID 36035133, 2022). "The effect of TMZ treatment has a strong correlation with the expression of methylguanine methyltransferase (MGMT) in glioma." (PMID 35683457, 2022). "Glioma subtype, 1p/19q co-deletion, grade II gliomas, IDH mutational status, and MGMT methylation were associated with lower-risk scores in TCGA and the two CGGA databases (p < 0.001)." (PMID 35252165, 2022). "For instance, recurrent gliomas exhibited transcriptional silencing of the MGMT gene, followed by dysfunction of the mismatch repair (MMR) system and hyperfunction of the DNA repair system." (PMID 35145081, 2022). "ANXA1 is useful as a prognostic biomarker in lower grade glioma patients with MGMT promoter methylation and a prognostic indicator and an immunotherapy marker for the tumour microenvironment in glioma." (PMID 35415239, 2022).
glioma (continued). "MGMT analogs, such as O6-benzylguanine and O6-(4-bromothenyl) guanine, can inactivate MGMT and sensitize gliomas to TMZ." (PMID 36147920, 2022). "It has been demonstrated that MGMT promoter methylation is a mechanism of MGMT regulation in gliomas, which is a favorable predictor of progression-free survival and overall survival in TMZ-treated patients." (PMID 35515137, 2022). "Interesting, in the current study, we found that HOXC6, MMP9 and SHOX2 expression were increased in the glioma tissues with promoter unmethylation of MGMT, while MYOD1 was reduced." (PMID 36118887, 2022). "Our research has discovered the potential signaling mechanism associated with C3G-mediated suppression of TMZ resistance in LN-18/TR cells through miR-214-5p, which can facilitate the treatment of MGMT-induced resistance in glioma cells." (PMID 35545654, 2022). "Subsequent to this study demonstrating an effect of exosomal methyltransferases on acquired cancer drug resistance, another independent research team evaluated such effect of exosomal MGMT in glioma TMZ resistance." (PMID 35682901, 2022). "There was a significant association between glioma grading and IDH1/2 (p < 0.05), 1p/19q (p < 0.05), MGMT (p < 0.05), Ki67 (p < 0.01), and MAGED2 (p < 0.01)." (PMID 35892426, 2022). "MGMT promoter methylation analysis gives sufficient prognostic information to merit its inclusion in the standard management of patients with high-grade gliomas, and in this study pyrosequencing seemed the better analytical method." (PMID 36551786, 2022). "The MGMT promoter methylation is also involved in the prognosis in glioma patients, and which is also an important indication for specific therapies." (PMID 35559019, 2022). "In gliomas, the methylation level of MGMT is also closely related to the efficacy of TMZ, where patients with hypomethylation of the MGMT promoter displaying an improved response to TMZ and survival outcomes." (PMID 36316307, 2022). "Isocitrate dehydrogenase, 1p/19q, and MGMT promoter methylation are three important features reported to serve as prognostic indicators for gliomas, with IDH-wt and IDH-mutant are two WHO classifications for GBM." (PMID 35874989, 2022). "Further, CNR of both, iodine density measurements and conventional CT measurements allowed for a separation of gliomas with IDH mutation and IDH wild type as well as MGMT promoter status." (PMID 36292183, 2022). "These novel chemical reagents would be good candidates, especially for those MGMT unmethylated gliomas or recurrent gliomas." (PMID 35774612, 2022). "For example, the status of O-6-methylguanine-DNA methyltransferase (MGMT) promoter methylation is a prognostic biomarker in glioma patients treated by temozolomide, but showing a minimal benefit for elderly patients." (PMID 35371978, 2022). "For DNA methylation in gliomas, a known example is the gene O6-methylguanine-DNA methyltransferase (MGMT)." (PMID 36338770, 2022). "The epigenetic suppression of MGMT by hypermethylation of cytidine–phosphate–guanine dinucleotides (CpG islands) in the promoter region is responsible for the decreased MGMT activity in glioma cells." (PMID 36009577, 2022). "In imaging analysis of central nervous system tumors, analyses that employ traditional radiomic analysis have been applied to combine imaging and molecular markers notably O6-methylguanine-DNA methyltransferase (MGMT), IDH, 1p19q, H3K27M." (PMID 35106480, 2022).